BSG (basigin (Ok blood group))
Description:
[Isoform 1]: Essential for normal retinal maturation and development (By similarity). Acts as a retinal cell surface receptor for NXNL1 and plays an important role in NXNL1-mediated survival of retinal cone photoreceptors. In association with glucose transporter SLC16A1/GLUT1 and NXNL1, promotes retinal cone survival by enhancing aerobic glycolysis and accelerating the entry of glucose into photoreceptors. May act as a potent stimulator of IL6 secretion in multiple cell lines that include monocytes. [Isoform 1]: (Microbial infection) Erythrocyte receptor for P.falciparum RH5 which is essential for erythrocyte invasion by the merozoite stage of P.falciparum isolates 3D7 and Dd2. [Isoform 2]: Signaling receptor for cyclophilins, essential for PPIA/CYPA and PPIB/CYPB-dependent signaling related to chemotaxis and adhesion of immune cells. Plays an important role in targeting monocarboxylate transporters SLC16A1/GLUT1, SLC16A11 and SLC16A12 to the plasma membrane. Acts as a coreceptor for vascular endothelial growth factor receptor 2 (KDR/VEGFR2) in endothelial cells enhancing its VEGFA-mediated activation and downstream signaling. Promotes angiogenesis through EPAS1/HIF2A-mediated up-regulation of VEGFA (isoform VEGF-165 and VEGF-121) and KDR/VEGFR2 in endothelial cells. Plays a key role in regulating tumor growth, invasion, metastasis and neoangiogenesis by stimulating the production and release of extracellular matrix metalloproteinases and KDR/VEGFR2 by both tumor cells and stromal cells (fibroblasts and endothelial cells). [Isoform 2]: (Microbial infection) Erythrocyte receptor for P.falciparum RH5 which is essential for erythrocyte invasion by the merozoite stage of P.falciparum isolates 3D7, Dd2, 7G8 and HB3. Binding of P.falciparum RH5 results in BSG dimerization which triggers an increase in intracellular Ca(2+) in the erythrocyte. This essential step leads to a rearrangement of the erythrocyte cytoskeleton required for the merozoite invasion. [Isoform 2]: (Microbial infection) Can facilitate human SARS coronavirus (SARS-CoV-1) infection via its interaction with virus-associated PPIA/CYPA. [Isoform 2]: (Microbial infection) Can facilitate HIV-1 infection via its interaction with virus-associated PPIA/CYPA. [Isoform 2]: (Microbial infection) First described as a receptor for severe acute respiratory syndrome coronavirus 2 (SARS-CoV-2), it is not required for SARS-CoV-2 infection. [Isoform 2]: (Microbial infection) Acts as a receptor for measles virus. [Isoform 2]: (Microbial infection) Promotes entry of pentamer-expressing human cytomegalovirus (HCMV) into epithelial and endothelial cells. Plays a role in neurite outgrowth.
Synonyms: EMMPRIN; HAb18G; TCSF; CD147; EMPRIN; 5F7; OK
Tractability: Small molecule: a structure with a bound ligand is known; it has a high-quality binding pocket. Antibody: a drug acting on it is in phase 2 or 3 trials; UniProt places it where antibodies can reach, with high confidence; its Gene Ontology location is reachable by antibodies, with high confidence; UniProt predicts a signal peptide or a membrane-spanning region. PROTAC: ubiquitination databases record sites on it; its protein half-life has been measured.
Target class: Membrane receptor
Gene: Protein-coding gene on chromosome 19 (571,277 to 583,498, forward strand). Ensembl gene ENSG00000172270.
Subcellular location: Melanosome; Cell membrane (Isoform 1); Photoreceptor inner segment; Cell projection, cilium, photoreceptor outer segment; Cell membrane (Isoform 2); Endosome; Endoplasmic reticulum membrane; Basolateral cell membrane; Cell membrane (Isoform 3); Cell membrane (Isoform 4)
Subcellular location (Human Protein Atlas): Vesicles; End piece; Mid piece; Principal piece
Pathways (Reactome):
Extracellular matrix organization: Degradation of the extracellular matrix; Integrin cell surface interactions
Disease: Defective SLC16A1 causes symptomatic deficiency in lactate transport (SDLT)
Drug ADME: Aspirin ADME
Hemostasis: Basigin interactions
Transport of small molecules: Proton-coupled monocarboxylate transport
Gene Ontology:
Molecular function: cadherin binding; protein binding; protein carrier chaperone; signaling receptor activity; cell-cell adhesion mediator activity
Biological process: neutrophil chemotaxis; photoreceptor cell maintenance; protein localization to plasma membrane; axon guidance; cell surface receptor signaling pathway; dendrite self-avoidance; homophilic cell-cell adhesion; neuron projection extension; anatomical structure morphogenesis; decidualization; embryo implantation; odontogenesis of dentin-containing tooth; response to cAMP; response to mercury ion; response to peptide hormone
Cellular component: basolateral plasma membrane; endoplasmic reticulum membrane; endosome; extracellular exosome; focal adhesion; melanosome; membrane; mitochondrion; plasma membrane; axon; Golgi membrane; photoreceptor inner segment; acrosomal membrane; photoreceptor outer segment; sarcolemma
Genetic constraint (gnomAD): Loss-of-function variants: 37 observed, 38.81 expected, observed/expected ratio (o/e) 0.95, 90% interval 0.73 to 1.25. The synonymous counts are far from expectation, so gnomAD's model fits this gene poorly and the ratio says little. Missense variants: 599 observed, 518.45 expected, observed/expected ratio (o/e) 1.16, 90% interval 1.08 to 1.24. Synonymous variants: 309 observed, 219.95 expected, observed/expected ratio (o/e) 1.4, 90% interval 1.28 to 1.54.
Homologues: Orthologues: chimpanzee BSG (96% identical), rat Bsg (66% identical), mouse Bsg (65% identical), guinea pig BSG (65% identical), macaque BSG (54% identical), tropical clawed frog bsg (49% identical), zebrafish bsg (44% identical), dog BSG (42% identical), Drosophila melanogaster Bsg (25% identical), Caenorhabditis elegans zig-11 (17% identical). Paralogues in human: NPTN (41% identical), EMB (19% identical), VSTM2L (11% identical).
Diseases named in the same sentence as BSG in open-access papers:
BSG is named in the same sentence as 378 diseases in open-access papers, as found by Europe PMC text mining. Sharing a sentence is not in itself a finding about the gene and the disease. The quoted sentences say what the papers report.
hepatocellular carcinoma (148 papers, 2005 to 2026). A malignant tumor that arises from hepatocytes. "BSG has been demonstrated to have a strong association with cancer, through its overexpression in breast, colon, and hepatocellular carcinomas." (PMID 35774118, 2022). "High BSG expression is also associated with poor prognosis in hepatocellular carcinoma patients." (PMID 38975467, 2024). "Higher BSG expression correlates with advanced tumor stages, worse differentiation, and increased metastasis and recurrence in hepatocellular carcinoma." (PMID 38975467, 2024). "Intriguingly, BSG has been identified as a potential target of non-coding RNA in hepatocellular carcinoma tumorigenesis." (PMID 36769187, 2023). "Monoclonal antibodies against BSG have also shown efficacy in treatment of hepatocellular carcinoma and hypervascular pancreatic tumours when administered alone or in combination with chemotherapy." (PMID 26099350, 2016). "Recently, it was found that BSG can mediate both apoptosis and autophagy, two main cell death patterns in human hepatoma cells." (PMID 24949431, 2014). "For example, BSG, a tumor-related glycoprotein, is highly expressed in hepatocellular carcinoma cells and fibroblasts." (PMID 24949431, 2014). "Based on previous findings, we hypothesized that different transcripts of BSG might exert distinct prognostic value for patients with hepatocellular carcinoma." (PMID 38975467, 2024). "An immunohistochemical study of a large number of normal and cancer tissues has shown that BSG is overexpressed in 112 out of 129 tumour samples with a very high incidence in glioblastoma, breast cancer, pancreatic cancer, hepatocellular carcinoma and squamous cell carcinomas, among others." (PMID 26099350, 2016). "A previous study has established a prognostic risk model for hepatocellular carcinoma (HCC) based on five ARGs (BAK1, SPP1, BSG, PBK, and DAP3)." (PMID 40901678, 2025).
COVID-19 (134 papers, 2020 to 2026). A disease caused by infection with severe acute respiratory syndrome coronavirus 2. "All these results suggested an underlying role of BSG in COVID-19 pathogenesis both in normal and cancer tissues." (PMID 38484369, 2024). "Analysis of the RNA-seq data demonstrated a significant association between the expression of BSG (CD147 gene) and the advancement of COVID-19." (PMID 37509657, 2023). "Recent findings on its potential involvement in SARS Coronavirus 2 (SARS-CoV-2) infection increased the need to better describe BSG expression patterns in various tissues." (PMID 35054026, 2022). "Vascular/cardiovascular inflammation and thrombosis occur in severe COVID-19, which may be linked to abundant BSG expression in cardiovascular and renal tissues." (PMID 33810391, 2021). "Notably, BSG is upregulated in a range of diseases that are considered risk factors of severe COVID-19, such as diabetes, obesity, pulmonary hypertension and thrombosis." (PMID 33810391, 2021). "On the basis of our findings, we suggest that BSG expression in the vasculature maybe an important driver that explains the heightened risk for severe disease and death observed in those >40 years of age with severe COVID-19." (PMID 33073064, 2020). "Our present work emphasized the value of targeting BSG in the treatment of COVID-19 and cancer, and also provided several novel insights for understanding the SARS-CoV-2 pandemic." (PMID 38484369, 2024). "We observed high expression levels of BSG in the heart and testis, which aligns with previous studies reporting heart damage and reproductive issues in COVID-19 patients." (PMID 38034398, 2023). "BSG also has high expressions in both healthy controls and COVID-19 patients in airway, nasal mucosa, and PBMC samples." (PMID 38034398, 2023). "Similar to previous findings, we observed the highest expression of BSG in SARS-CoV-2-RNA-positive cells when analysing COVID-19 patient single-cell datasets." (PMID 38034398, 2023). "On the other hand, BSG had high expression in both healthy controls and COVID-19 patients across airway, nasal mucosa, and PBMC samples." (PMID 38034398, 2023). "TMPRSS2 was positively correlated with the ratio of late EMT in COVID-19 and BSG was negatively correlated with the ratio of late EMT in COVID-19." (PMID 36248845, 2022). "Exome sequencing and analysis of a smaller cohort of 131 COVID-19 patients from Italy for genetic variants of TMPRSS2, PCSK3, DPP4, and BSG genes identified 17 variants." (PMID 33092637, 2020). "We analyzed 131 COVID-19 patients by exome sequencing and examined the genetic variants of TMPRSS2, PCSK3, DPP4, and BSG genes." (PMID 32867305, 2020). "The spatial spots for a small spatial transcriptomics sequencing dataset of bronchial and alveolar tissue derived from COVID-19 patients display highly expressed BSG in many regions of both bronchial and alveolar areas, suggesting the pivotal role of BSG in SARS-CoV-2 infection process." (PMID 38617561, 2024). "BSG contributes to the COVID-19 symptoms on account of its expression in the inflammatory, infected and tumor cells, and thus forming the basis of the possible COVID-19 therapy." (PMID 38484369, 2024). "Thus, BSG is a key factor in COVID-19 infection and progression and can serve as a new target for effective treatment of COVID-19." (PMID 38484369, 2024). "Importantly, an open-label clinical trial of Meplazumab, a humanized therapeutic monoclonal antibody against BSG, which showed significant improvements in patients with COVID-19." (PMID 38484369, 2024). "In addition to COVID-19, BSG is also reported to be involved in the tumorigenesis of multiple tumors, such as melanoma, liver hepatocellular carcinoma (LIHC), and hypopharyngeal squamous cell carcinoma." (PMID 35646943, 2022). "This study revealed that COVID-19-related BSG was differently expressed in various human cancers." (PMID 35646943, 2022).
COVID-19 (continued). "Although we highlighted hACE2 as a binding partner of SARS-CoV-2, a number of studies presented different docking partners of the human host to SARS-CoV-2 infections, such as NRP1, L-SIGN(CLEC4M), DC-SIGN(CD209), and CD147(BSG)." (PMID 35816517, 2022). "For example, through its previously-described role in the development of the immune system, BSG could indirectly influence COVID-19 clinical progression." (PMID 33432067, 2021). "Moreover, BSG is overexpressed in both COVID-19 patients and cancer patients." (PMID 38484369, 2024). "On the other hand, BSG/CD147, which belongs to the Ig superfamily is expressed in several tissues like the brain, heart, liver, kidney etc and might play a complex role in COVID-19 and possibly contribute to the worse prognosis of patients with other co-morbidities." (PMID 35517495, 2022). "Evidently, the violin plot-based analysis and the heatmap analysis showed significantly higher expression of BSG and NRP1 in ACE2-positive COVID-19-infected brain cells as compared to the control group." (PMID 37239234, 2023). "Further analysis of the correlation with invasion genes showed that the entry factor genes (BSG, FURIN, and CTSL) were positively correlated with the ratio of early EndMT in COVID-19, and CTSL was positively correlated with the ratio of early EndMT in IPF." (PMID 36248845, 2022). "BSG is a vital entrance of SARS-CoV-2 into human cells and is upregulated in both COVID-19 patients and tumor patients." (PMID 35646943, 2022). "TMPRSS2 and ACE2 expression were upregulated in COVID-19 patients but BSG, CTSL, FURIN expression was higher in IPF patients, suggesting their role in increased myofibroblast expression in COVID-19." (PMID 36248845, 2022). "Therefore, BSG is a potential predictive biomarker for tumors, which may serve as a biological modulator of tumor and COVID-19 and improve the management of cancer patients during the period of the COVID-19 pandemic." (PMID 35646943, 2022). "Interestingly, we identified the BSG protein, also named CD147, as a DEP in COVID-19 patient samples." (PMID 35842415, 2022). "ACE2, MX1, and BSG/CD147 expression constitute a molecular signature that reliably differentiates COVID-19 and non-COVID-19 patients." (PMID 34494942, 2021). "There are two important target proteins in human for COVID-19, angiotensin-converting enzyme-2 (ACE2) and basigin (BSG); therefore, researchers in the area of system biology utilize these proteins to make host–pathogen interactions network with high confidence." (PMID 33230386, 2020). "Above all, we failed to collect samples from patients diagnosed with both COVID-19 and cancer, and thus, we could not directly identify whether these patients with differently expressed BSG expression had poor prognosis in our study." (PMID 35646943, 2022). "The expression of MX1, MX2, ACE2, and BSG/CD147 can cluster individuals with and without COVID-19 through principal component analysis, which indicated that the expression levels of MX1 and MX2 between patients with and without COVID-19 are remarkably different." (PMID 35620480, 2022). "Clearly, a full understanding of BSG interactions with SARS-CoV-2 will provide valuable mechanistic insight and could identify new therapeutic targets and/or provide additional insight for experimental drugs currently in trials for the prevention and treatment of severe COVID-19." (PMID 33073064, 2020).
breast carcinoma (115 papers, 2006 to 2026). "BSG has been implicated in breast cancer progression, and is a marker of the aggressive basal-like and triple-negative subtypes, as well as being associated with poor overall survival within these patients." (PMID 35839778, 2022). "Among the strongest was the dependency on FOXA1 transcription factor knockout and protein levels of basigin (BSG; also known as CD147), a plasma membrane protein expressed in breast cancer cells." (PMID 35839778, 2022). "LDHA overexpression has been reported in lung adenocarcinoma, CAIX in breast cancer and oral squamous cell carcinoma, MCT4 in bladder and breast cancer, and BSG in acute myeloid leukemia." (PMID 36678382, 2022). "Some studies have provided evidence that downregulation of BSG via lentivirus vector-based RNAi decreased cell proliferation, matrigel invasion, and tumor formation in breast cancer, especially in MCF-7 breast cancer cells." (PMID 32891152, 2020). "Recent experimental studies showed that breast cancer patients with low hsa-let-7b (2nd in the prediction list) expression had poor prognoses which indicated that hsa-let-7b might act as cancer suppressor gene in breast cancer development and progression by inhibiting the expression of BSG." (PMID 30142158, 2018). "Key genes, such as BSG, TGFBI, and ADAM17, were already shown as having well-established roles in breast cancer biology." (PMID 41374933, 2025). "FOXA1-BSG association occurred in luminal (luminal A and B) and HER2-positive (non-basal) breast cancer cell lines, in which BSG protein abundance is low relative to basal cell lines." (PMID 35839778, 2022). "Finally, only 1 (BCAS4/BCAS3), 1 (BSG/NFIX), 2 (STX16/RAE1, RAB22A/MYO9B) and 0 fusions have been reported by all the tools within the considered breast cancer cell lines." (PMID 28114882, 2017). "To assess ADAM12-mediated shedding of full-length endogenous BSG, we stably expressed ADAM12 in MCF7 human breast cancer cells, which express no detectable endogenous ADAM12." (PMID 31013576, 2019).
melanoma (76 papers, 2010 to 2025). A malignant, usually aggressive tumor composed of atypical, neoplastic melanocytes. "Given the well-documented role of MMP9 in cancer metastasis and the direct effect of BSG ubiquitination on cell invasiveness in our present study, TRAF6-mediated BSG ubiquitination represents a novel mechanism underlying BSG-dependent melanoma metastasis." (PMID 26769849, 2016). "And BSG participated in regulating complex I activities and apoptosis in melanoma via interacting with mitochondrial NDUFS6." (PMID 38484369, 2024). "In terms of tissues, previous reports have identified differently expressed BSG in a few cancers, such as melanoma and LIHC." (PMID 35646943, 2022). "Our previous studies demonstrated that BSG can regulate melanoma invasion and metastasis through induction of MMPs and VEGF." (PMID 26769849, 2016). "In particular, we demonstrated that BSG is a novel interacting partner of TRAF6, which regulates BSG membrane recruitment, BSG-dependent MMP9 expression and melanoma cells invasiveness via K63-linked ubiquitination." (PMID 26769849, 2016). "Its inhibition has been tested in cell lines for the treatment of malignant melanomas with promising results, and therefore BSG/CD147 inhibition could be investigated in neuroblastomas." (PMID 38398114, 2024). "Previous study confirmed the existence of BSG in human melanoma cell mitochondria." (PMID 38484369, 2024). "We also investigated the correlation of the seven prognostic-associated TBCs between MMP-related genes (MMP2, MMP9, MMP7, MMP14, BSG, EGFR, MMP1, MMP3) and EMT-associated genes (TWIST1, VIM, CDH2, ACTA2, ZEB1), which also indicated a central role of TBCs in melanoma." (PMID 33194704, 2020). "Furthermore, TRAF6 directly interacts with BSG, which is important for the expression of MMPs during melanoma metastasis and induces the ubiquitination of BSG." (PMID 27791197, 2016). "Interestingly, four genes known to be related to cancer cell stemness in malignant melanoma (ALDH1A3, BSG, NGFR, SOX2) were expressed at significantly high levels in CTCs with a high “platelet signature” (p = 0.0204, 0.0012, 0.0183, 0.0200, respectively)." (PMID 40003901, 2025). "Furthermore, TRAF6 can directly interact with and ubiquitinate BSG leading to MMP9 induction, which serves as a mechanism for melanoma invasion and metastasis." (PMID 26769849, 2016).